CRP (C-reactive protein)
Diseases named in the same sentence as CRP in open-access papers (continued):
Sharing a sentence is not in itself a finding about the gene and the disease.
depression (continued). "Our hypothesis was that elderly with depression or Alzheimer’s disease had higher levels of IL-1β, IL-6, TNF-α and CRP than controls without psychiatric disorders." (PMID 30104698, 2018). "The acute phase protein C-reactive protein (CRP) at baseline predicted changes in fatigue as measured by Functional Assessment of Cancer Therapy—Fatigue Scale in patients receiving chemotherapy and was independent of depression." (PMID 25954147, 2015). "Compared with non-depressed individuals, patients with depression show elevated levels of proinflammatory cytokines, including interleukin-1(IL1), interleukin-6(IL6), and tumor necrosis factor-alpha(TNF-α), as well as the systemic inflammation biomarker C-reactive protein(CRP)." (PMID 41179571, 2025). "Elevated CSF levels of C-reactive protein (CRP), an acute phase protein and a commonly applied inflammatory marker, showed a significant correlation with the severity of motor (H&Y, UPDRS III) and non-motor (cognition, depression and fatigue) symptoms in PD and APS." (PMID 35204829, 2022). "The findings showed that persons with higher BMI PRS, CRP PRS and MDD PRS are more likely to have ↑WS depression v. non-↑WS depression and ↓WS depression, while those with lower PRS for alcohol daily use were more likely to have non-↑WS depression rather than ↑WS depression." (PMID 32624019, 2022).
metabolic syndrome (1,361 papers, 2001 to 2026). A cluster of metabolic risk factors for CARDIOVASCULAR DISEASES and TYPE 2 DIABETES MELLITUS. "H. pylori has been reported to contribute to the development of CVD in a variety of ways, including causing inflammation, endothelial dysfunction, dyslipidemia, iron and vitamin B12 malabsorption, and elevating CRP levels." (PMID 40102932, 2025). "CRP is a prominent biomarker for inflammation and cardiovascular risk and was recently found to be a marker for metabolic syndrome." (PMID 39761962, 2025). "The association remained significant when adjusting for metabolic syndrome, age and sex (aOR = 1.32, 95% CI 1.02–1.72) and also in Model IV, which included further adjustment for hs-CRP (OR = 1.33, 95% CI 1.02–1.74)." (PMID 39825928, 2025). "In a cohort of 257 overweight/obese women, both TSA and CRP increased with greater metabolic-syndrome burden; however, only TSA remained associated after BMI adjustment." (PMID 41301440, 2025). "The numbers of studies reporting the association of cardiovascular disease (CVD), stroke, dyslipidemia, C-reactive protein (CRP), formal education, and low socioeconomic status with the risk of AMD were four, two, two, two, two, and two, respectively." (PMID 40771483, 2025). "This inflammatory environment is reflected by higher CRP levels, which have been associated with various components of the metabolic syndrome." (PMID 40002762, 2025). "Studies showed that an elevated CRP level serves as a key marker indicating an increased risk of cardiovascular disease in patients with metabolic syndrome." (PMID 41133134, 2025). "Serum progranulin levels are significantly associated with inflammatory markers, including C-reactive protein and interleukin-6, and have also been shown to be positively correlated with components of metabolic syndrome." (PMID 41010769, 2025). "For example, elevated markers such as C-reactive protein (CRP) and interleukin (IL)−6 have been linked to an increased risk for metabolic syndrome, cardiovascular disease, and mental disease later in life." (PMID 40186267, 2025). "High-sensitivity C-reactive protein (hs-CRP) is a marker of systemic inflammation and is associated with developing dyslipidemia." (PMID 39859220, 2025). "Our results revealed significant associations between smoking and dyslipidemia with elevated hs-CRP levels, highlighting the complex interplay between cardiovascular risk factors and systemic inflammation." (PMID 40004724, 2025). "Specifically, for every 0.34 mmol/L higher TSA, the likelihood of meeting ≥3 metabolic-syndrome criteria was nearly doubled after controlling for BMI (p < 0.0001), whereas the CRP association was attenuated by BMI adjustment." (PMID 41301440, 2025). "C-reactive protein is an acute-phase reactant that is elevated in metabolic syndrome and T2D, and it has been linked to CVD risk and mortality in PWoH, with levels above 3 μg/mL indicating high risk." (PMID 40160348, 2025). "Chronic conditions including type 2 diabetes, cardiovascular disease, dyslipidemia, and autoimmune diseases (e.g., lupus, scleroderma) are associated with sustained CRP elevation." (PMID 40566547, 2025). "C-reactive protein (CRP) is produced in the liver in response to an acute inflammatory stimulus and is linked to metabolic syndrome and coronary artery disease." (PMID 40951890, 2025). "Logistic regression showed a significant association between hs-CRP concentrations and dyslipidemia (OR 2.08, 95% CI: 1.81–2.39, p < 0.001)." (PMID 39859220, 2025). "The study concluded that measuring CRP enhances risk assessment beyond traditional metabolic syndrome definitions." (PMID 40943152, 2025). "On the other hand, hs-CRP is associated with dyslipidemia, positively correlated with TG, and negatively correlated with HDL-C." (PMID 40172775, 2025). "Hs-CRP is a more precise test than CRP, elevated levels being linked to atherosclerosis and CV disease, type 2 diabetes, metabolic syndrome, autoimmune disorders and cancer." (PMID 40529359, 2025).
metabolic syndrome (continued). "We assessed the presence of features associated with metabolic syndrome including blood pressure, type II diabetes status (determined by blood levels of A1c), and plasma levels of C-reactive protein (CRP) and leptin." (PMID 38172612, 2024). "Their research demonstrated that greater consumption of fruits and vegetables is linked to a reduced risk of metabolic syndrome, possibly due to decreased CRP levels." (PMID 39337053, 2024). "Inflammatory markers showed significant associations with parameters related to the metabolic syndrome, including CRP with LDL-C and HDL-C, and FIB with ALT and ACR." (PMID 39109081, 2024). "People with the coexistence of elevated CRP levels and dyslipidemia had the highest risk of stroke among male." (PMID 39247228, 2024). "Data showed that serum lipid levels were unrelated to hs-CRP values, but there was a reported association between hs-CRP and the development of dyslipidemia." (PMID 39200151, 2024). "AIP had positive associations with males, BMI, current smoking, T2DM, dyslipidemia, hs-CRP, creatinine, uric acid, FBG, HbA1c, TG, TC, LDL-C, and non-HDL-C, while negative associations with age and HDL-C (all p < 0.05)." (PMID 39009987, 2024). "HA1c and CRP, two biomarkers associated with dyslipidemia and HDL-C dysfunction, were then added sequentially to the model." (PMID 39765763, 2024). "Specifically, we investigated the association between high-sensitivity C-reactive protein (CRP) and the metabolic syndrome severity Z-score (MetS-Z), and explored the combined effect of their cumulative exposure on the risk of tumour development." (PMID 38386717, 2024). "In the general population, an elevated CRP has been associated with the presence of metabolic syndrome and subsequent metabolic risk." (PMID 39408201, 2024). "In patients with metabolic syndrome, cruciferous vegetables are linked to lower plasma CRP content, while regular berry intake decreases CRP, IL-6, and circulating vascular cell adhesion molecule 1 content, a biomarker of vascular damage." (PMID 39770983, 2024). "It has been demonstrated that higher levels of C-reactive protein (CRP) in obese women with PCOS are associated with susceptibility to dyslipidemia and diminish endothelial function in these individuals." (PMID 39634187, 2024). "Analysis of different types of dyslipidemia in combination with abnormal inflammation levels revealed that high LDL cholesterol combined with high levels of CRP are a risk factor for the development of stroke." (PMID 39247228, 2024). "In a population cohort (n = 839, 40–65 y, 58% F), low IGFBP-1 (below the median) and high CRP (in the highest tertile) were together associated with a dramatic increase in the risk of metabolic syndrome (odds ratio 14)." (PMID 39595651, 2024). "Previously, it was described that high scores were associated with lower HOMA-IR and highly sensitive C-reactive protein, which is a useful scale to determine metabolic syndrome." (PMID 38674256, 2024). "Based on above studies, we conducted our study to assess the combined effect of elevated-CRP levels and dyslipidemia on the overall risk of stroke in the middle-aged and geriatric Chinese population." (PMID 39247228, 2024). "Both GlycA and CRP were significantly associated with mutations that increase susceptibility to metabolic syndrome and were also associated with inflammatory diseases and chronic conditions which were ascribed to inflammageing." (PMID 38785970, 2024). "T2DM and metabolic syndrome are associated with a chronic state of low-grade inflammation, with increased serum levels of CRP and pro-inflammatory cytokines, such as IL-6, IL-1β and TNF-α." (PMID 38140319, 2023). "A double-blind randomized controlled trial conducted on adult males with metabolic syndrome (n = 250) found that turmeric supplementation caused a significant reduction in serum CRP after 8 weeks of treatment." (PMID 37566728, 2023).
metabolic syndrome (continued). "Nuts, such as almonds and walnuts, reduce inflammation and oxidative stress by decreasing the levels of C-reactive protein, IL-6, endothelial adhesion molecules, and oxLDL, thereby reducing the risk for metabolic syndrome." (PMID 37175603, 2023). "CRP levels ranging from 3 to 10 mg/L are induced by chronic diseases, such as metabolic syndrome, and higher CRP levels have been associated with physical activity and other lifestyle factors, such as smoking." (PMID 37049401, 2023). "In human populations, dietary magnesium intake is inversely associated with cardiometabolic disease, metabolic syndrome, and colorectal cancer, as well as serum or plasma C-reactive protein (CRP)." (PMID 37603433, 2023). "For example, depressive symptoms have been found to be associated with inflammation as gauged by C-reactive protein levels and a range of metabolic syndrome components." (PMID 37974151, 2023). "This study found that the association between exposure to ERI and the metabolic syndrome was mediated by CRP serum concentrations." (PMID 36981836, 2023). "In Colombia, in males national air force staff, a WC cut-off point of 88 cm was associated with cardiometabolic alterations, including dyslipidemia and elevation of the acute phase reactant C-reactive protein." (PMID 38028452, 2023). "The authors found that a high score of DII is associated with a higher number of CRP components in the second and third tertile of Chinese patients with metabolic syndrome." (PMID 36627587, 2023). "CRP is observed to rise as the number of conditions associated with metabolic syndrome increases, and is elevated in obese patients who experience a corresponding decrease in CRP with weight loss." (PMID 37521410, 2023). "Growing evidence suggests that the consumption of TFAs is associated with dyslipidemia and the activation of systemic inflammatory responses, such as elevated CRP, interleukin-6, and tumor necrosis factor." (PMID 37710270, 2023). "In a few studies, it was found that increased CRP levels or dyslipidemia before beginning exercise were associated with greater reductions in CRP." (PMID 36381804, 2022). "Age, gender, body mass index, central obesity, spot urinary proteinuria, fasting blood glucose, poor glycemic control, creatinine, and Hs-CRP were all associated with different dyslipidemia patterns in multivariate logistic regression analyses." (PMID 36404351, 2022). "Periodontal disease is also known to elevate the level of several systemic biomarkers that cause endothelial dysfunction and dyslipidemia, such as the C-reactive protein (CRP), low-density lipoprotein (LDL), TNF-α, IL-6, and IL-1β." (PMID 35845078, 2022). "The C allele of the HNF1A rs735396 polymorphism was previously associated with the components of metabolic syndrome in the Tunisian population, as well as altered CRP levels, whereas the T allele was associated with the development of pancreatic cancer." (PMID 35741825, 2022). "It was reported that, there was an association between C-reactive protein (CRP) and development of metabolic syndrome." (PMID 36407366, 2022). "Metabolic syndrome components, including WG, have been previously associated with high levels of CRP and uric acid, while CRP is highly predictive of subsequent risk of cardiovascular events and DM in apparently healthy men and women." (PMID 35892742, 2022). "Increased circulating CRP is an indicator of ongoing inflammation and is considered a risk factor for developing metabolic syndrome." (PMID 35910956, 2022). "In the univariate Cox proportional hazards analysis, CONUT score (as a continuous variable), age, dyslipidemia, BMI, history of CVDs, and CRP were significant predictors of all-cause mortality." (PMID 35684116, 2022). "High-sensitivity C-reactive protein (hs-CRP) levels and metabolic syndrome (MetS) are known to be associated with an increased incidence of different cancers." (PMID 35927639, 2022).
metabolic syndrome (continued). "One other way to elaborate on this aspect is to evaluate if metabolic syndrome signatures of LD subjects, namely, higher TG, CRP and hepatic enzymes and lower HDL-C, consistently associate to the sign of change of cmiRs-320." (PMID 35733784, 2022). "CRP is an acute-phase inflammatory protein that increases in obese patients and represents a marker for the early diagnosis of metabolic syndrome and cardiovascular risk in obese children." (PMID 36612926, 2022). "This multiethnic urban cohort study provides insights into the association between child maltreatment and comorbid metabolic syndrome in people with current depressed mood, and the potential mediating effect of the inflammatory marker CRP." (PMID 35910956, 2022). "Increased 5-HIAA is also associated with high-sensitivity C-reactive protein, a marker of chronic low-grade inflammation underlying metabolic syndrome." (PMID 36466649, 2022). "When the data were stratified by individuals’ CRP level, the association between carbohydrate intake and metabolic syndrome was significant only among those with a low level of CRP (OR 1.84, 95% CI 1.21–2.80, highest vs. lowest quartile, p-trend = 0.003)." (PMID 34578975, 2021). "We adopted CRP as a variable as previous studies have shown the association between CRP and metabolic syndrome." (PMID 33739984, 2021). "Low adherence to dietary recommendations was further associated with dyslipidemia, higher uric acid, and C-reactive protein levels." (PMID 33531632, 2021). "A higher level of CRP is related to an increased risk of metabolic syndrome and its components, which are associated with underlying inflammatory processes." (PMID 34578975, 2021). "In this study, CRP, a well-established marker of systemic inflammation in metabolic syndrome, tend to be identified as an independent risk factor of cancer in young adults." (PMID 34527591, 2021). "Our study highlights the role of sports participation during adolescence as an important protective factor for both metabolic syndrome risk and CRP through direct and indirect roles." (PMID 34508111, 2021). "The current study has clear practical implications, such as highlighting sports participation as an important protective factor for metabolic syndrome risk, trunk fat, and CRP." (PMID 34508111, 2021). "Our aim was to analyze the association between somatic maturation and alterations in metabolic syndrome (METs) risk and C-reactive protein (CRP), focusing on the effect of changes in trunk fat and sports practice." (PMID 34508111, 2021). "Lamers and colleagues presented evidence that patients with specific atypical features show associations with immuno-metabolic outcomes including IL-6, CRP and metabolic syndrome components, both cross-sectionally and longitudinally." (PMID 33653423, 2021). "The present study aimed to analyze the association between somatic maturation and prospective changes in metabolic syndrome risk and CRP, considering sports participation and trunk fat as potential mediators through a structural equation model." (PMID 34508111, 2021). "CRP was measured in this study to link LGMs to an inflammatory status, as low-grade inflammation is often associated with metabolic syndrome." (PMID 34086828, 2021). "In a randomized clinical trial, a modified alternate-day fasting diet was reported to be more effective than CR on weight loss and reduction of CRP levels in patients with metabolic syndrome." (PMID 34867458, 2021). "Considering missing data as well as outliers, the final sample was composed of 139 adolescents with complete data for metabolic syndrome risk and CRP analysis." (PMID 34508111, 2021). "In the present study, we observed a stronger association between carbohydrate intake and metabolic syndrome among those with low levels of CRP." (PMID 34578975, 2021). "Metabolic syndrome and CRP were associated with increased total cancer mortality [HR = 1.33, 95% CI 1.04–1.70]." (PMID 32977765, 2020).